FTO (FTO alpha-ketoglutarate dependent dioxygenase)
Diseases named in the same sentence as FTO in open-access papers (continued):
Sharing a sentence is not in itself a finding about the gene and the disease.
cancer (continued). "From the Oncomine database, high expression of FTO in various human cancers including ccRCC was found." (PMID 35961973, 2022). "The inhibitors and regulators of m6A modification regulators have been explored as therapeutic approaches for treating cancer, such as FTO inhibitors (including rhein, R-2HG, IOX3, and FB23) and METTL3/METTL14 inhibitors (3-deazaadenosine)." (PMID 35154270, 2022). "To explore the underlying mechanism of m6A demethylase FTO-mediated autophagy in ccRCC, we identified SIK2 as a key regulator that plays a decisive role in malignant tumor proliferation and distant metastasis including lung metastasis." (PMID 36263177, 2022). "FTO has recently been shown to play an m6A-dependent role in multiple biological processes, such as cancer cell apoptosis, proliferation, migration, invasion, metastasis, cell-cycle, differentiation, stem cell self-renewal and so on." (PMID 35784761, 2022). "Mechanistically, FTO demethylates downstream target mRNAs, affects m6A levels, and exerts pro- or anti-cancer effects." (PMID 36358640, 2022). "Among them, there were 12 m6A regulatory genes, including IGF2BP1, with a significantly higher expression in LUAD tissues compared with para-carcinoma tissues, while FTO, METTL14, WTAP, and ZC3H13 showed a significantly lower expression." (PMID 36249006, 2022). "The expression of FTO is elevated in the LUSC, and FTO inhibits cancer formation by inhibiting m6A methylation, which inhibits expression of the oncogene MZF1 eventually." (PMID 34957092, 2021). "FTO is another potential target for cancer therapy, and small molecules against FTO are being developed." (PMID 34485297, 2021). "FTO inhibitors are the most well‐researched candidates targeting m6A modification in cancer therapy, with several FTO inhibitors that increase the m6A abundance on RNAs having already been successfully identified." (PMID 34586737, 2021). "In contrast to the plethora of studies on m6A writers and readers in cancer, less is known about the m6A demethylase, FTO." (PMID 33922187, 2021). "More and more evidence shows that FTO plays different roles in the occurrence and development of different cancers." (PMID 33952279, 2021). "FTO has been involved in regulating multiple aspects of cancer biology, including cell proliferation, migration, invasion and apoptosis." (PMID 34076564, 2021). "Some observations of FTO suggest that it plays a crucial role in the proliferation and apoptosis of some cancer cells, also glucose and lipid metabolism." (PMID 34630412, 2021). "FTO removes the m6A modification and modulates the stability of mRNA, which ultimately leads to the alteration of pathogenesis in various types of cancer." (PMID 34630412, 2021). "METTL14 was down-regulated in all 11 cancer types while FTO and ALKBH5 were down-regulated in most cancer types except for KIRC." (PMID 33718187, 2021). "FTO removes the N6-methyladenosine (m6A) modification from genes and plays a critical role in cancer development." (PMID 33966037, 2021). "In recent years, researchers have used FTO as a target to develop FTO inhibitors, hoping to make new breakthroughs in cancer treatment." (PMID 35004679, 2021). "Curiously, our results on m6A eraser expression are in line with those reported for other cancers, in which FTO and ALKBH5 were also found to be overexpressed." (PMID 34683137, 2021). "As an “eraser” of m6A, FTO can remove m6A modification, regulate mRNA stability, and eventually lead to changes in the pathogenesis of various cancers." (PMID 33952279, 2021). "Given the critical roles of the m6A regulatory proteins in cancers, m6A modification ‘eraser’ FTO appears to be a good drug target in cancer therapy." (PMID 33731118, 2021). "Considering that the functions of autophagy are highly context dependent, the specific role of FTO in cancer remains contradictory, despite the suppression of FTO in PARPi-resistant OC cells and CSC OC cells." (PMID 34895230, 2021).
cancer (continued). "FTO, as an m6A demethylase, has been shown to be involved in the occurrence and development of various cancers through different downstream genes." (PMID 34218271, 2021). "The expression of FTO was negatively correlated with clinical cancer metastasis-related factors, such as cancer local microvascular density and CA19-9 concentration in serum." (PMID 34211849, 2021). "Recently, FTO has been the most attractive target for developing specific inhibitors targeting m6A modulators for cancer treatment." (PMID 34239358, 2021). "Such interaction of these inhibitors with FTO resulted in a strong antitumor effect in multiple types of cancers." (PMID 33807762, 2021). "Several scientists have reported that FTO is overexpressed in various human cancers and that it stimulates cancer cell metabolism, thus inducing tumorigenesis and chemoresistance." (PMID 33634966, 2021). "Emerging evidence suggests that FTO and m6A RNA methylation regulate their functions in cancer and other diseases through different downstream gene targets depending on the context and cell lineage." (PMID 33846348, 2021). "We found that the FTO expression was significantly reduced in cancer tissues compared with that in ANTs, which indicated a lower malignant potential and a higher overall survival rate." (PMID 34499008, 2021). "Western blot analysis of fractions eluted from the column showed that FTO appeared in almost all the fractions, suggesting that in cancer tissues and cancer cell lines the protein exists in highly diverse forms, ranging from monomers up to large complexes." (PMID 34639211, 2021). "Whereas, ZC3H13 and FTO were highly expressed in normal tissues and low expressed in cancer tissues." (PMID 34521394, 2021). "The overexpression of FTO facilitated cancer progression by stabilizing heat shock transcription factor 1 (HSF1) in a YTHDF2-dependent way." (PMID 34804925, 2021). "Recent studies have shown that FTO plays m6A-dependent roles in tumorigenesis and progression in several cancers." (PMID 34218271, 2021). "It is well known that meclofenamic acid, R-2-hydroxyglutarate, and MO-I-500 inhibit the activity of FTO and display anti-cancer activity." (PMID 35004679, 2021). "FTO is highly expressed in several human cancers, and it enhances tumorigenesis and cell transformation." (PMID 32296573, 2020). "Declined mRNA levels of ALKBH5 and FTO were related to a shortened overall and cancer-specific survival following nephrectomy." (PMID 33015074, 2020). "It was also reported that some drugs with antitumor activity, such as R-2-hydroxyglutarate (R-2HG), inhibited proliferation/survival of FTO-high cancer cells via targeting FTO/m6A/MYC/CEBPA signaling." (PMID 32754191, 2020). "This is consistent with our previous discovery that seven out of nine ALKBH proteins, including FTO, are overexpressed in fast proliferating cancer cells." (PMID 32747736, 2020). "In conclusion, R-2HG can inhibit the proliferation/survival of cancer cells with high FTO expression levels by targeting the FTO/m6A/MYC/CEBPA signaling cascade." (PMID 32398132, 2020). "Several studies have shown that FTO regulates the function of cancer stem cells, cancer cell growth, and self-renewal via the demethylation of m6A RNAs." (PMID 32033081, 2020). "The PI3K/AKT/mTOR pathway has been implicated in the development of various types of cancer regulated by m6A proteins, including METTL3/WTAP in AML, METTL3 in RCC/PDAC, ALKBH5 in EOC, and FTO in melanoma and EC." (PMID 32513173, 2020). "Entacapone has an anti-cancer effect, but it needs to be further clarified if it through inhibiting FTO." (PMID 33304380, 2020). "A study notes that knockdown of FTO inhibits the proliferation of cancer cells and induces them to apoptosis, suggesting that FTO plays an oncogenic role." (PMID 32612834, 2020). "Based on the oncogenic role of FTO in several cancers, inhibitors that target FTO have attracted scientific interests, but more information about its role in BC is needed." (PMID 33505967, 2020).
cancer (continued). "Adjacent genes (RPGRIP1L, RBL2, IRX3, IRX5) regulated by FTO SNPs are also involved in the occurrence and progression of cancer in various ways." (PMID 33304380, 2020). "Considering the role of carbohydrates in cancer cell metabolism, this study aimed to investigate the mediating role of the FTO gene in the effect of dietary carbohydrates on cancer cells." (PMID 31447604, 2019). "More importantly, increasing proofs reveal that dysfunction of FTO can contribute to cancer development, such as acute myeloid leukemia, melanoma, breast cancer and lung cancer." (PMID 31827395, 2019). "Our findings reflect a discrepancy in FTO/ALKBH5 action as the demethylase regulating N6meA level in mRNA in normal vs cancer cells." (PMID 31519943, 2019). "We found that MA2 repressed cell viability through inhibiting the demethylase activity of FTO, providing new insights into the mechanisms of MA suppressing cancer cell proliferation." (PMID 31333841, 2019). "It was reported that the level of FTO gene expression is higher in cancer cells than in normal cells and the cells adjacent to cancer tissue." (PMID 31447604, 2019). "It was assumed that an increase in the FTO gene expression can increase glycolysis in the cancer cells by effect on the PI3K/AKT signaling pathway." (PMID 31447604, 2019). "Using western blot (WB) analysis, we detected overexpression of seven out of the nine ALKBH proteins (ALKBH1, 2, 3, 4, 5, 8, and FTO) in HNSCC cancer tissues, as compared to the surrounding, unaffected tissue." (PMID 31519943, 2019). "Further, silencing of ALKBH1, 4, 5, and FTO markedly decreased HeLa cancer cell survival, suggesting involvement of these ALKBHs in cancer development by DNA/RNA/protein modification." (PMID 31519943, 2019). "IHC showed that FTO was steadily expressed in normal kidney tissues but was declined in cancer counterpart and lost in the later stage (Figure 1D1‐2)." (PMID 30648791, 2019). "Surprisingly, despite high expression of FTO/ALKBH5 in cancer tissue, the level of N6meA was also significantly elevated, in comparison to normal tissue." (PMID 31519943, 2019). "This review summarised what has been recently discovered about the effects of dietary carbohydrate on cancer cells and tried to determine the mediating role of the FTO gene in these effects." (PMID 31447604, 2019). "Other FTO‐induced cancers have not been investigated so far, and additional studies need to be performed to explore the eraser role of FTO in regulating these cancers." (PMID 30039919, 2018). "Just recently, the potential role of FTO in cancer initiation and progression by down‐regulating the overall m6A level has been investigated." (PMID 30039919, 2018). "Collectively, evidence is emerging that FTO plays critical oncogenic roles in various types of cancers as an m6A demethylase, and post-transcriptionally regulates expression of a number of functionally important target genes through m6A-dependent mechanisms." (PMID 30105001, 2018). "Notably, SNPs outside of intron 1 of FTO could also be associated with cancer risk." (PMID 30105001, 2018). "Given the critical roles of FTO in cancers, the development of selective and effective inhibitors targeting FTO holds potential to treat cancers." (PMID 30105001, 2018). "The findings of FTO function in response to the treatment of cervical cancer expands our understanding of m6A role in cancer development." (PMID 30062093, 2018). "R-2-hydroxyglutarate(R-2HG), which accumulates in isocitrate dehydrogenase 1/2 (IDH1/2) mutant cancers, can increase global m6A via inhibiting FTO, resulting in the decrease of MYC/CEBPA mRNA stability and inhibition of leukemia proliferation." (PMID 30062093, 2018). "Inhibition of the RNA demethylases ALKBH5 and FTO is a potential strategy to target cancer stem cells." (PMID 28533023, 2017). "It seemed that FTO rs9939609 SNP played different roles in the development of different cancer, as well as in different populations." (PMID 28881622, 2017).
cancer (continued). "Furthermore, the FTO inhibitor FB23/FB23-2 can effectively inhibit the proliferation and migration of cancer cells by suppressing FTO 128-130." (PMID 41362736, 2026). "Recent studies have highlighted the critical role of N6-methyladenosine (m6A) modification in cancer progression, yet the specific function of the m6A regulatory factor FTO in TNBC remains unclear." (PMID 42264087, 2026). "The same demethylase, such as FTO, plays different functions in different cancers." (PMID 40332101, 2025). "Specifically, an inhibitor named 18 097 reduces mRNA stability and expression of PPARγ and C/EBP-α/β by inhibiting FTO, leading to decreased lipid uptake and oxidation in cancer cells, and effectively restraining breast cancer growth and lung metastasis in vivo." (PMID 41446042, 2025). "FTO has an anti-cancer effect in cancer development and is downregulated in ccRCC." (PMID 40332101, 2025). "FTO’s role in cancer is complex and highly context dependent." (PMID 40722726, 2025). "In human cancer cells, FTO localizes to the cytoplasm and favors cancer progression." (PMID 39995976, 2025). "Beyond FTO, other m6A regulators, such as “writers”, also exhibit dual roles in cancer." (PMID 39990672, 2025). "In the past 5-10 years, research on the impact of FTO on cancer progression has begun to emerge." (PMID 39967906, 2025). "Demethylation of m6A RNA by FTO may regulate the stability of different RNA targets in various cancers." (PMID 40722726, 2025). "Unlike previous studies in which FTO was used to promote tumourigenesis, a study focused on OC revealed that FTO expression levels are decreased in this type of cancer and inhibit tumourigenesis in vivo by affecting cAMP signalling pathways and blocking the self-renewal process of OC stem cells." (PMID 40356909, 2025). "Overall, these studies suggested that FTO may have multifunctional roles across different cancer types and tissues." (PMID 40621649, 2025). "Previous studies have highlighted mechanistic roles of FTO in other cancers." (PMID 41141648, 2025). "Finally, current drugs targeting m6A mainly focus on METTL3 and FTO, with research predominantly centred on cancer." (PMID 39779466, 2025). "Most research regarding the role of FTO in cancer progression has emerged over the past decade." (PMID 40722726, 2025). "Since FTO has been demonstrated the crucial role plays in the malignant behavior of diverse cancers, we wondered whether FTO is involved in pNENs progression." (PMID 39990672, 2025). "Similarly, inhibiting FTO weakens cancer cell self-renewal capacity by blocking m6A modification on mRNAs associated with ovarian cancer (OC) stem cell properties." (PMID 41446042, 2025). "However, findings regarding FTO remain contradictory, as it promotes PD-L1 expression in some cancers but appears suppressed in others." (PMID 41280938, 2025). "Although these findings highlight the potential for FTO to be a therapeutic target in cancer treatment, recent studies have indeed demonstrated that FTO promotes LUAD progression, for example by regulating autophagy, the miR‐181b‐3p/ARL5B axis, or the stability of USP7 mRNA." (PMID 40621649, 2025). "FTO has also been reported to mediate resistance of pancreatic ductal adenocarcinoma to gemcitabine through stabilization of lncRNA LINC01134, which is upregulated in this cancer and is associated with gemcitabine resistance." (PMID 40243425, 2025). "FTO also plays critical roles in cancer stem cell self-renewal and immune evasion." (PMID 40000966, 2025). "Knockdown of FTO suppressed cancer growth in a mouse xenograft model by increasing the m6A level of platelet‐derived growth factor C (PDGFC) mRNA, promoting PDGFC mRNA degradation by binding to YTHDF2, decreasing PDGFC secretion, and inhibiting the AKT signaling pathway." (PMID 40448344, 2025). "The FTO gene plays a significant role in the progression of cancer." (PMID 40391584, 2025).
cancer (continued). "Single-nucleotide polymorphisms (SNPs) in FTO and ALKBH5 are associated with cancer risk." (PMID 40361322, 2025). "Furthermore, the downregulation of FTO in lung cancer inhibited the growth of cancer cells both in vitro and in vivo through the repression of USP7 expression in an m6A-dependent manner." (PMID 40136363, 2025). "However, despite the clear ability of FTO to demethylate m6Am, a series of subsequent studies showed that FTO also demethylates m6A in cells, and that m6A demethylation accounts for the main aspects of FTO biology, especially its ability to promote cancer." (PMID 41279954, 2025). "The development of FTO inhibitors provides additional therapeutic solutions for cancer treatment." (PMID 40823087, 2025). "Given the oncogenic role of FTO in many cancer types, rhein may act as a potential lead for new treatment." (PMID 40483535, 2025). "These phenomena suggest that the impact of the FTO gene on cancer development may be cancer specific." (PMID 39897037, 2025). "As research continues to uncover the complexities of FTO’s role, it may offer novel therapeutic opportunities to target cancer growth and overcome treatment resistance." (PMID 39744011, 2024). "Notably, FTO has been reported to be frequently overexpressed in a wide range of cancer types, including breast cancer, prostate cancers, pancreatic cancer, leukemia, and so on." (PMID 38545555, 2024). "Notably, clinical data derived from Kaplan–Meier plots indicate a strong correlation between elevated levels of FTO and poor patient prognosis in cancer patients." (PMID 39335515, 2024). "In EC, FTO, along with YTHDF1 upregulates the expression of 17beta‐hydroxysteroid dehydrogenase 11 (HSD17B11), thereby promoting the formation of lipid droplets in EC cells and cancer development, which is associated with a poor prognosis for patients with EC." (PMID 38721006, 2024). "In contrast, when FTO levels are reduced, the malignant development of cancer cells is inhibited." (PMID 39678510, 2024). "However, the tumor-promoting and suppressive roles of FTO in different cancer types must be taken into account." (PMID 39280246, 2024). "FTO was initially discovered in the early 1990s as the first RNA-m6A demethylase involved in lipid regulation, and it was later found to play a significant role in cancer." (PMID 39192357, 2024). "Furthermore, m6A RNA levels in the PB of MC38 cancer models were upregulated, whereas the expression of FTO and ALKBH5 decreased." (PMID 38439072, 2024). "Based on TCGA‐CESC cohort and GEO dataset, FTO expression levels in HPV‐positive cancer patients were significantly higher than those in HPV‐negative cancer patients and could predict advanced FIGO stage." (PMID 39692250, 2024). "Knocking down FTO alleviated the cancer-like behavior of RA-FLS." (PMID 38481810, 2024). "FTO is upregulated in many cancers, and its high expression correlates with lower overall survival." (PMID 39329974, 2024). "Intriguingly, the biological function of FTO is cancer context dependent." (PMID 39268470, 2024). "In summary, our results demonstrated that targeting FTO could significantly suppress cancer cell growth in a ferroptosis dependent manner." (PMID 38600610, 2024). "We postulate that a similarly conserved epitranscriptomic mechanism involving m6A235 demethylating activity by ALKBH5 and/or FTO may contribute to the induction of ATF4 mRNA expression in cancer cells under stress conditions." (PMID 39199320, 2024). "As the first identified m6A RNA demethylase, the significance of FTO in cancer research is growing." (PMID 38956367, 2024). "Additionally, association analysis of the PCa-associated risk loci in the cancer genome atlas program (TCGA) data unveiled genetic variations near the WTAP, HNRNPA2B1, and FTO genes as significant expression quantitative trait loci." (PMID 38610981, 2024).